REN (renin)
Diseases named in the same sentence as REN in open-access papers (continued):
Sharing a sentence is not in itself a finding about the gene and the disease.
Hypertension (continued). "In addition, Renal infarction typically manifests with: Acute flank pain commonly unilateral, Microscopic or gross hematuria, Inflammatory responses such as fever (less common), and lastly Hypertension due to activation of the renin-angiotensin system." (PMID 40729806, 2025). "Individuals diagnosed with “low renin” hypertension may demonstrate tendencies towards sodium and water retention, indicating the potential benefit of utilizing antihypertensive medications like TDs and CCBs." (PMID 40106408, 2025). "This could be the result of chronic hyperglycemia in the as of hypertension activating the renin-angiotensin system, which led to an increase in the level of Angiotensin II (AII) in vitreous fluid in patients with diabetics macular edema and DR." (PMID 40162316, 2025). "The renin-angiotensin system (RAS) is central to cardiovascular diseases such as hypertension and cardiomyopathy, yet the functions of many RAS genes remain unclear." (PMID 40907688, 2025). "Consequently, low renin levels in autonomic failure have been reported to have a protective effect against hypertension complications." (PMID 40342812, 2025). "This process may activate the sympathetic nervous system and the renin-angiotensin-aldosterone system, both of which are known to raise blood pressure, exacerbating hypertension." (PMID 40708645, 2025). "Secondly, insulin resistance may trigger abnormal activation of the renin-angiotensin-aldosterone system, contributing to hypertension development." (PMID 41024162, 2025). "In addition, visceral adipocytes secrete angiotensin, which not only arouses the activation of renin–angiotensin system but also induces hypertension, glomerular hyperfiltration, and renal injury." (PMID 40979159, 2025). "CACNA1D mutations cause arterial hypertension in rats and a CACNA1D polymorphism is linked to increased blood pressure in white humans, independent of aldosterone, in keeping with the father’s arterial hypertension despite a normal aldosterone/renin ratio." (PMID 41561050, 2025). "Mercury’s role in hypertension pathophysiology may involve endothelial dysfunction, renin–angiotensin system (RAS) disturbance, and inflammation." (PMID 41614871, 2025). "In the present cohort, where most participants did not exhibit hypertension or obesity, we found the association to be predominantly of a renin-dependent nature." (PMID 39148442, 2025). "It is reasonable to speculate that CD PRR/renin-dependent activation of intrarenal Aldo contributes to the upregulation of renal medullary α-ENaC, which promotes 2K1C-induced hypertension via its sodium-retaining action in the distal nephron." (PMID 40909559, 2025). "Therefore, Clinical strategies should focus on intensive diabetes management (target HbA1c < 7.0%), hypertension control (< 130/80 mmHg) using renin-angiotensin inhibitors and fluid management to prevent endothelial dysfunction." (PMID 40314886, 2025). "Therefore, HDL-induced alterations in AT1R expression in other vascular cells in SHR cannot be excluded as additional mechanisms through which HDL reverses vascular remodeling and attenuates hypertension via its interaction with the renin-angiotensin system." (PMID 40799826, 2025). "The coexistence of hypertension may further reduce cardiac output through the activation of the renin-angiotensin-aldosterone system and the sympathetic nervous system." (PMID 40951819, 2025). "This higher risk may have been owing to overactivation of the renin‐angiotensin‐aldosterone system (RAAS), vascular changes that can cause arterial stiffness and hypertension, and systemic inflammation in CKD patients." (PMID 40395862, 2025). "These may result in “page kidney” which refers to renin‐angiotensin‐mediated hypertension secondary to renal hypoperfusion following long‐standing compression of renal parenchyma by a subcapsular collection." (PMID 40443501, 2025).
Hypertension (continued). "Finally, vitamin D has been shown to suppress components of the renin–angiotensin–aldosterone system (RAAS), which is often upregulated in pre-eclampsia and implicated in hypertension and vasoconstriction." (PMID 40508834, 2025). "Additionally, IR activates inflammatory pathways and the renin-angiotensin-aldosterone system, worsening hypertension and accelerating diabetic kidney disease." (PMID 40297336, 2025). "Patients with focal replacement fibrosis had significantly higher ambulatory systolic blood pressure and longer duration of hypertension with more impaired left ventricular structure while diffuse interstitial fibrosis was more related to abnormalities in plasma renin and aldosterone." (PMID 40395817, 2025). "Importantly, renin–angiotensin–aldosterone system (RAAS) inhibitors widely used in hypertension treatment have been shown to have a beneficial effect when used with ICI therapy in cancer patients." (PMID 40563574, 2025). "Several intertwined factors contribute to kidney damage, including hyperfiltration leading to proteinuria and adipokines driving oxidative stress and inflammation, insulin resistance, and activation of the renin–angiotensin–aldosterone system (RAAS) alongside hypertension." (PMID 40796899, 2025). "Factors that may influence the development of hypertension in children includevascular structure, mechanics and function, oxidative stress, hyperinsulinemia,insulin resistance, hyperlipidemia, renin-angiotensin-aldosterone elements, andimmune abnormalities." (PMID 40927078, 2025). "It is characterized by severe hypertension with hypokalemia due to excessive renin production." (PMID 40546339, 2025). "Together, these results support the idea that CD PRR/renin-dependent generation of intrarenal Aldo may play a primary role in the pathogenesis of ischemic nephropathy and a secondary role in hypertension development during renovascular constriction." (PMID 40909559, 2025). "After the addition of HRP, Nile red fluorescence staining and Oil Red O staining quantification showed that HRP significantly reversed the increase in lipid content induced by renin in HepG2 cells, confirming the key role of (P)RR in hypertension combined with MAFLD." (PMID 40650317, 2025). "This indicates that the renin-angiotensin system may influence both hypertension and depression, though the mechanisms remain unclear." (PMID 40110085, 2025). "Finally, metabolic stress, combined with factors such as hypertension or dysfunction of the renin–angiotensin axis, promotes fibrosis through the activation of TGF-β and other profibrotic pathways." (PMID 40724891, 2025). "High circulating levels of adiponectin have also been reported as predictors of incident cardiovascular and renal events in treated hypertensive patients and to be released upon blockade of the renin-angiotensin system in patients with essential hypertension to improve insulin sensitivity." (PMID 40272732, 2025). "Multiple antihypertensive medications (angiotensin‐converting enzyme inhibitors, angiotensin receptor blockers, beta‐blockers, diuretics) that frequently serve as first‐line agents for essential hypertension interact with the renin–angiotensin–aldosterone system (RAAS)." (PMID 40113595, 2025). "Several protective actions of polyphenols in hypertension have been revealed, including enhancement of endothelial function, inhibition of oxidative stress, improvement of NO availability, and inhibition of the renin–angiotensin system (RAS)." (PMID 39339768, 2024). "This randomized, single-blinded, titration-to-effect aims to investigate whether targeted treatment in low-renin hypertension with MRA is better compared to standard antihypertensives in terms of blood pressure control and end-organ protection." (PMID 39026100, 2024).
Hypertension (continued). "Although social and community gatherings happen occasionally in rural South African populations, the consumption of unhealthy diet such as high dietary sodium in the long-term can lead to dysregulation of the renin-angiotensin system, contributing to hypertension." (PMID 39138450, 2024). "Despite PA being a highly prevalent and curable cause of hypertension, assays for aldosterone and renin required for its diagnosis are not widely available in this region." (PMID 38261997, 2024). "With the progression of the disease, lumen stenosis may develop and lead to renin-angiotensin-aldosterone system activation, resulting in hypertension." (PMID 38243321, 2024). "Downregulation of eNOS in the renal medulla is shown to induce hypertension in rats, whereas significant constitutive expression of NO synthases in the juxtaglomerular apparatus of the kidneys are negative regulators of renin secretion and thereupon RAAS system activation." (PMID 38999899, 2024). "Despite evidence supporting treatment that differs from standard practice, low-renin hypertension as a condition distinct from essential hypertension is overlooked due to renin and aldosterone concentrations being neither routinely requested nor used to guide initial therapy." (PMID 39026100, 2024). "Hypertension during pregnancy may arise from hormonal changes, including estrogen, progesterone, and relaxin, which affect the renin-angiotensin-aldosterone system (RAAS), leading to salt and water retention and increased plasma volume." (PMID 39156021, 2024). "Common mechanisms, such as upregulation of the renin-angiotensin-aldosterone system, oxidative stress, inflammation, and immune system activation, likely contribute to the close relationship between diabetes and hypertension." (PMID 38694275, 2024). "This could be explained by that the patients on steroid therapy that have hypertension developed significant sodium retention, decreased renin and aldosterone levels, and hypervolemia." (PMID 39396026, 2024). "It is hypothesised that the low renin in the context of hypertension reflects excess MR activation and/or salt reabsorption due to abnormalities in renal sodium handling in the distal nephrons of the kidneys." (PMID 38200100, 2024). "Such observational data are subject to confounding by indication for the prescription of such medications although the effect of renin-angiotensin system inhibition cannot be attributed to comorbidities, such as hypertension, which were of a similar frequency between patient cohorts." (PMID 38774915, 2024). "Patients with renin-independent aldosteronism who present with normotension and mild to moderate hypertension are described as subclinical PA or mild PA and may progress to overt PA in the future." (PMID 39713051, 2024). "Around 70% of patients diagnosed with hypertension exhibit increased levels of renin." (PMID 38632457, 2024). "Androgen signaling may play a crucial role in this gender disparity, as previous studies have shown that increased androgen receptor (AR) activity and testosterone levels may influence hypertension by altering the renin-angiotensin-aldosterone system." (PMID 38632649, 2024). "This review outlines the molecular mechanisms of hypertension in IH, which include the regulation systems of reactive oxygen species (ROS) that activate the renin–angiotensin system (RAS) and catecholamine biosynthesis in the sympathetic nervous system, resulting in hypertension." (PMID 38276286, 2024). "The clinical picture may include a palpable flank mass, hypertension due to elevated renin, hematuria, and hypercalcemia (paraneoplastic syndrome)." (PMID 39493139, 2024). "Additionally, soy isoflavones have been found to combat hypertension by influencing components within the renin-angiotensin-aldosterone system." (PMID 38454401, 2024). "Fourth, hypertension, renin–angiotensin, and angiopathy mutually promote each other." (PMID 39669374, 2024).
Hypertension (continued). "By fine-tuning drug release profiles and enhancing drug uptake at specific sites, LBDDS can potentially target renin-angiotensin-aldosterone system components, sympathetic nervous system pathways, and endothelial dysfunction, all of which play crucial roles in hypertension pathophysiology." (PMID 38410720, 2024). "Recognizing treatment-resistant hypokalemia in licorice toxicity is clinically important, as it underscores the need to consider licorice toxicity in cases of unexplained hypokalemia and hypertension, especially when standard therapies are ineffective and renin-aldosterone levels are suppressed." (PMID 39498427, 2024). "One drug related to REN has been approved as a renin inhibitor used to manage hypertension." (PMID 39397782, 2024). "Studies on human patients and experimental models reveal specific mechanisms related to programmed hypertension in the kidney, such as reduced nephron number, oxidative stress, epigenetic regulation, activation of the renin–angiotensin system (RAS), and sodium transporters." (PMID 39201737, 2024). "Given this, ACE and renin inhibition stands as one of the strategies in hypertension treatment." (PMID 39000571, 2024). "Renin is a member of the renin-angiotensin-aldosterone system, which, via its active peptide angiotensin II, contributes to atherosclerosis development, not only by promoting hypertension but also through multiple direct actions on vessels." (PMID 38811951, 2024). "Hypertension activates the renin-angiotensin-aldosterone system (RAAS) and the sympathetic nervous system, contributing to vasoconstriction, sodium and water retention, and myocardial hypertrophy, further exacerbating hypertension and cardiovascular disease progression." (PMID 39678236, 2024). "Alicylen is a representative renin inhibitor, and its application in diabetes has been in the clinical application research stage, mainly focusing on the protective effect on DN, diabetes complicated with hypertension, and target organs." (PMID 38645437, 2024). "The research findings of this study will improve our understanding of the pathophysiology and management of hypertension with low renin and may inform future hypertension guidelines." (PMID 39026100, 2024). "Posttransplant hypertension is caused by multifactorial pathogenesis, including pretransplant hypertension, donor hypertension, renin secretion from the native kidney, graft dysfunction, recurrent disease and immunosuppressive treatment, which negatively affects graft and patient survival outcomes." (PMID 39726791, 2024). "Renal cell carcinoma may contribute to hypertension by activating the renin–angiotensin system and affecting renal structure and function." (PMID 39272451, 2024). "Angiotensin II-induced hypertension and heart failure model recapitulate renin–angiotensin–aldosterone system activation and hypertensive heart disease, aiding in understanding hypertension-induced heart failure pathophysiology and assessing renin–angiotensin–aldosterone system (RAAS) inhibitors." (PMID 39432214, 2024). "TRPM8, as a cold sensor, may alleviate cold-induced hypertension related to the renin–angiotensin–aldosterone system by inhibiting Ang II-induced cytoplasmic Ca2+influx and mitochondrial calcium overload after being activated by menthol." (PMID 38255767, 2024). "Moreover, monocytes act on vasculature during the hypertension through the overactivation of renin–angiotensin system and adverse vascular remodeling." (PMID 39394117, 2024). "Specifically, the correlation between psoriasis and hypertension might be grounded in shared pathways such as the altered renin-angiotensin system, endothelial dysfunction, and increased oxidative stress." (PMID 38541672, 2024). "The prevalence of PA might be higher than currently reported, since a continuum of renin-independent aldosterone secretion shows an extended spectrum of PA from normotension to severe arterial hypertension." (PMID 38586159, 2024).
Hypertension (continued). "Typically, normal plasma renin levels are measured (so called “low‐renin hypertension”)." (PMID 39613722, 2024). "Indeed, studies demonstrated that collecting duct renin is important for potassium excretion and is involved in Ang II-dependent hypertension." (PMID 39273497, 2024). "A Spanish population study of non-pregnant women who carried the GG phenotype of the REN (rs5707) polymorphism revealed a strong correlation with hypertension development." (PMID 38411777, 2024). "Augmented synthesis of the PRR in distal nephron segments, particularly in the collecting duct, has been described in experimental animal models of hypertension including chronic Ang II infusions, renin transgenic rats, and 2K1C Goldblatt hypertensive rat models." (PMID 39337535, 2024). "This also means that what we currently recognize as severe hypertension and hypokalemic PA may be only the “tip of the iceberg” in the spectrum of renin-independent aldosteronism and excessive MR activation." (PMID 39713051, 2024). "In rats, excessive zinc intake induced hypertension by activating the renin-angiotensin system." (PMID 39830063, 2024). "ACE inhibitors are a commonly used medication in the treatment of hypertension and may target menopause induced renin-angiotensin-aldosterone system dysregulation, although animal studies suggest that this is only one pathway involved." (PMID 38861130, 2024). "Previous studies had shown that hyperinsulinemia may regulate hypertension by activating renin-angiotensin, further reducing renal blood flow, and increasing the reabsorption of urate and xanthine, leading to hyperuricemia." (PMID 38974578, 2024). "Chronic hyperglycaemia, a primary factor in diabetic complications, contributes to hypertension through mechanisms like renin–angiotensin–aldosterone system (RAAS) hyperactivation, sympathetic overactivity, and nitric oxide suppression, leading to myocardial and vascular remodelling." (PMID 39681809, 2024). "Two multicenter, open-label, nonrandomized dose-escalation studies were conducted in which the administration of esaxerenone as a monotherapy and as an add-on to renin-angiotensin system inhibitor therapy was compared in Japanese patients with hypertension and moderate kidney dysfunction." (PMID 39857638, 2024). "Hormonal evaluation was done in only around half of our cohort, but then only a quarter had all adrenal hormones (serum/plasma cortisol post-dexamethasone, metanephrines and aldosterone/renin ratio if hypertension or hypokalemia are present) done which are recommended when evaluating adrenal tumors." (PMID 38581593, 2024). "Renin-angiotensin system inhibitors may be used to manage hypertension and reduce proteinuria in patients with renal complications." (PMID 38669382, 2024). "A positive relationship between albumin and potassium may inhibit the renin–angiotensin–aldosterone system, thus preventing hypertension development." (PMID 38779492, 2024). "Additionally, uric acid can stimulate the renin-angiotensin system and reduce the levels of natriuretic peptides, further contributing to hypertension." (PMID 38256692, 2024). "PA is a state of hypertension caused by inappropriate aldosterone secretion in response to salt intake, which is independent of renin secretion." (PMID 39877848, 2024). "Nonetheless, our recent investigation revealed that L-NAME-induced hypertension is linked not to heightened, but rather to the normal or reduced activation of the renin–angiotensin II system (RAS) in both serum and LV tissue." (PMID 38672089, 2024). "Beta-blockers alleviate hypertension by reducing renin release." (PMID 38424404, 2024). "SBP was also higher in men than in women, in accordance with previous research suggesting that the higher prevalence of hypertension in men may be due to interactions between oestrogens/testosterone and the renin–angiotensin–aldosterone system." (PMID 38674834, 2024).